SNHG9 (small nucleolar RNA host gene 9)
Synonyms: DKFZp686N06141; NCRNA00062
Gene: Long non-coding RNA gene on chromosome 16 (1,964,526 to 1,965,513, forward strand). Ensembl gene ENSG00000255198.
Gene Ontology:
Biological process: RNA processing
Cellular component: nucleolus
Diseases named in the same sentence as SNHG9 in open-access papers:
SNHG9 is named in the same sentence as 28 diseases in open-access papers, as found by Europe PMC text mining. Sharing a sentence is not in itself a finding about the gene and the disease. The quoted sentences say what the papers report.
glioblastoma (9 papers, 2020 to 2024). The most malignant astrocytic tumor (WHO grade IV). "A previous study demonstrated that up-regulating SNHG9 was associated with poor prognosis in glioblastoma, as this lncRNA promoted tumor cell proliferation via regulating Wnt2 and miR-199a-5p." (PMID 35887228, 2022). "LncRNA small nucleolar RNA host gene 9 (SNHG9) is also elevated in glioblastoma tissues and it is associated with a lower OS (p = 0.0106) and PFS (p = 0.0014) in patients with glioma." (PMID 33652661, 2021). "SNHG9 has also been demonstrated to be over-expressed in glioblastoma samples in association with poor survival of patients." (PMID 33634032, 2020). "The SNHG9 gene has been implicated in several cancer types, including glioblastoma, pancreatic cancer, and non-small cell lung cancer (SCLC), although its function in HS remains unknown." (PMID 38792557, 2024). "Small nucleolar RNA host gene 9 (SNHG9) 551 nucleotide base pair intergenic lncRNA located on chr16p13.3 have all been linked to the onset and progression of distinct cancers including pancreatic cancer 21, glioblastoma 22, lung cancer 23, ovarian cancer." (PMID 34539877, 2021). "SNHG9, when increased in glioblastoma stem cells (GSCs), functions as a ceRNA for miR-326 and promotes the development of GSCs." (PMID 36741904, 2022). "Mechanistically, SNHG9 downregulates miR-199a-5p, leading to the upregulation of the Wnt2 axis in glioblastoma cells." (PMID 33652661, 2021). "SNHG9 has been identified as an oncogene in pancreatic cancer and glioblastoma, but its function is unclear." (PMID 33898523, 2021). "SNHG9 is overexpressed in glioblastoma and upregulate Wnt2 by downregulating miR-199a-5p to promote the proliferation of cancer cells." (PMID 32738890, 2020). "SNHG9 has a role in suppression of miR-199a-5p expression and enhancement of Wnt2 expression in glioblastoma cells." (PMID 33634032, 2020). "As SNHG9 can promote the expression of Wnt2 in glioblastoma, we speculated that downregulation of SNHG9 may also lead to inactivation of the WNT signaling in OA." (PMID 32738890, 2020). "Small nucleolar RNA host gene 9 (SNHG9) is a membrane-lipid-related LncRNA that has been shown to regulate the proliferation of pancreatic cancer cells and glioblastoma cells." (PMID 33898523, 2021). "Small nucleolar RNA host gene 9 (SNHG9), a recently identified lncRNA, has been reported to interact with Wnt2 to participate in glioblastoma." (PMID 32738890, 2020).
hepatoblastoma (6 papers, 2021 to 2025). Hepatoblastoma (HB) is a malignant hepatic tumor and is the most common pediatric liver cancer. "Our study findings, demonstrate that SNHG9 is significantly upregulated in hepatoblastoma tissue and is closely associated with poor prognosis in hepatoblastoma." (PMID 34539877, 2021). "In summary, to our acknowledgement, this study is the first to explore the biological function and underlying molecular mechanisms of SNHG9 in hepatoblastoma tumorigenesis." (PMID 34539877, 2021). "In the current study, we elucidate the critical role of SNHG9 in hepatoblastoma progression and the underlying mechanisms." (PMID 34539877, 2021). "Next, to better understand the significance of SNHG9 upregulation in hepatoblastoma, we performed a correlation test to elucidate the association between SNHG9 expression and patients' clinicopathological characteristics." (PMID 34539877, 2021). "ROC and Kaplan-Meier analysis showed potential prognostic and diagnostic importance of SNHG9 in hepatoblastoma." (PMID 34539877, 2021). "ROC analysis showed SNHG9 has high sensitivity and specificity for identification of hepatoblastoma tumors, thus it could be a potential diagnostic biomarker, and therapeutic target for the treatment and early diagnosis of HB patients." (PMID 34539877, 2021). "However, the exact function and underlying mechanism of SNHG9 in hepatoblastoma tumorigenesis is unknown and needs to be explored." (PMID 34539877, 2021). "However, the biological function and underlying molecular mechanisms of SNHG9 in hepatoblastoma tumor progression are unknown and need to be elucidated." (PMID 34539877, 2021). "For instance, SNHG9 promotes carcinogenesis in hepatoblastoma by downregulating miR-23a-5p and upregulating Wnt3a." (PMID 36741904, 2022). "With regard to liver cancers, it was shown that SNHG9 promoted hepatoblastoma tumorigenesis via miR-23a-5p/Wnt3a axis." (PMID 35887228, 2022). "Eventually, we elucidate that SNHG9 promotes hepatoblastoma tumorigenesis via the miR-23a-5p/WNt3a axis." (PMID 34539877, 2021). "Next, to elucidate the biological role of SNHG9, in hepatoblastoma tumorigenesis, we knockdown and overexpressed SNHG9 in HB cell lines and performed CKK-8 and clonogenic assays." (PMID 34539877, 2021). "A xenograft in-vivo tumorgenicity test was performed to elucidate the role of SNHG9 hepatoblastoma in tumorigenesis." (PMID 34539877, 2021). "All these findings provide strong evidence that SNHG9 promotes hepatoblastoma tumorigenesis via downregulating miR-23a-5p and upregulation Wnt3a." (PMID 34539877, 2021). "Conversely, a significant reduction in SNHG9 expression was observed among SNHG9 knockdown/downregulated hepatoblastoma (HUH6 & HepG2) cell lines." (PMID 34539877, 2021). "The effect of SNHG9 silencing and overexpression on hepatoblastoma (HUH6 and HepG2) cell proliferation, colony formation, and cellular apoptotic activity were investigated." (PMID 34539877, 2021). "In this study, we performed in-vivo and in-vitro test to demonstrate that SNHG9 contribute to cisplatin resistance in hepatoblastoma cell lines (HepG2 & HUH6)." (PMID 34539877, 2021). "SNHG9 was found to be significantly upregulated in primary hepatoblastoma tissue compared to adjacent normal hepatic tissue." (PMID 34539877, 2021). "Further, we examined the relative SNHG9 expression in hepatoblastoma (HUH6 & HepG2) cell lines and found a remarkable high expression of SNHG9 in hepatoblastoma (HUH6 & HepG2) cell lines than in QSG7701 normal hepatic cell lines (QSG7701)." (PMID 34539877, 2021). "Next, we observed the subcellular distribution of SNHG9 in hepatoblastoma (HUH6 & HepG2) cells and revealed that SNHG9 was predominately located in the cytoplasm like that of the majority lncRNA." (PMID 34539877, 2021). "Next, we downregulated and upregulated SNHG9 expression in hepatoblastoma cell lines and then determined cell proliferation (CCK-8), colony formation, and cellular apoptosis activity." (PMID 34539877, 2021).
hepatoblastoma (continued). "SNHG9 role in Cisplatin drug resistance in hepatoblastoma was also determined." (PMID 34539877, 2021). "However, SNHG9 overexpression on HB cells enhances cell proliferation and clonogenic activity, thus confirming its involvement in the pathophysiology of hepatoblastoma tumorigenesis." (PMID 34539877, 2021). "SNHG9 expression among hepatoblastoma tumor patients was significantly upregulated." (PMID 34539877, 2021). "SNHG9 promotes hepatoblastoma tumorigenesis through wnt3a/miR-23a-5p axis." (PMID 34539877, 2021). "Furthermore, we investigated the effect of SNHG9 silencing and overexpression on hepatoblastoma cellular apoptosis activity." (PMID 34539877, 2021). "SNHG9 was conspicuously upregulated in the hepatoblastoma tissue and HB cell lines." (PMID 34539877, 2021). "Hence, SNHG9/miR-23a-5p/wnt3a might be a novel and promising therapeutic target for hepatoblastoma patients." (PMID 34539877, 2021). "SnoRNA host gene 9 (SNHG9) is associated with the progression of distinct human cancers, but, its specific molecular mechanisms in hepatoblastoma is not unknown." (PMID 34539877, 2021). "Similarly, research has identified that lncRNAs TUG1, HOXA-AS2, OIP5-AS1, ZFAS1, SNHG9, NBR2 and MIR205HG are significantly upregulated in HB cells and enhance cell proliferation, migration or invasion in hepatoblastoma." (PMID 38390281, 2024).
pancreatic cancer (6 papers, 2019 to 2024). "In another study, the upregulation of SNHG9 was reported to be a potential biomarker for pancreatic cancer." (PMID 32738890, 2020).
breast carcinoma (4 papers, 2022 to 2025). "SNHG9 (Small Nucleolar RNA Host Gene 9) is a lipid-binding lncRNA highly expressed in breast cancers." (PMID 35406602, 2022). "Recently, a study revealed the lncRNA SNHG9 as a tumor-promoting factor in breast cancer, and the expression of SNHG9 was positively correlated with breast cancer progression." (PMID 35701841, 2022). "Another lncRNA associated with breast cancer is the small nucleolar RNA host gene 9 (SNHG9), which correlates with breast cancer progression and other types of cancer and was found to interact with PA (phosphatidic acid) and Large Tumor Suppressor Kinase 1 (LATS1)." (PMID 40801625, 2025).
glioma (4 papers, 2021 to 2022). A benign or malignant brain and spinal cord tumor that arises from glial cells (astrocytes, oligodendrocytes, ependymal cells). "The forest plot shows that EPB41L4A.AS1, GDNF.AS1, HAR1A, LINC00237, SLC25A21.AS1, SNA13.AS1, and WDFY3.AS2 are the protective factors with HR < 1, while LINC00092, LINC00265, LINC00339, LINC00665, PAXIP1.AS2, SNHG16, SNHG9 and SOCS2.AS1 are risk factors with HR>1 in glioma patients." (PMID 35273128, 2022).
lung carcinoma (3 papers, 2020 to 2022). "A high expression of SNHG9, an lncRNA, was validated in 78 lung tumor tissues, and the expression was inversely associated with overall survival of lung cancer patients (p = 0.002)." (PMID 32294932, 2020). "SNHG9 expression was positively associated with stage of lung cancer (p < 0.05)." (PMID 32294932, 2020). "The results obtained from the clinical specimens provide further evidence that the dysregulation of SNHG9 contributes to lung cancer development and progression." (PMID 32294932, 2020). "Since SNHG9 was one of the lncRNAs that displayed the highest expression level in bronchial epitheliums of sputum from lung cancer patients, we performed in vitro and in vivo analyses to investigate its possible role in tumorigenesis of NSCLC." (PMID 32294932, 2020). "These in vivo findings in ectopic xenograft mouse models are consistent with the in vitro observations, and hence support that suppression of SNHG9 could inhibit in vivo tumorigenicity of lung cancer cells." (PMID 32294932, 2020). "Furthermore, of the ncRNAs that displayed the highest expression level in bronchial epitheliums of sputum from lung cancer patients, only SNHG9 was further analyzed by in vitro and in vivo approaches in this present study." (PMID 32294932, 2020). "Importantly, SNHG9 expression in tumor tissues is positively related to advanced stages of lung cancer and inversely correlated with survival of the patients." (PMID 32294932, 2020). "In addition, suppression of SNHG9 decreased the colony formation, migration, and invasion of the lung cancer cells." (PMID 32294932, 2020). "In addition, the Kaplan–Meier Curve indicated that the lung cancer patients with a high SNHG9 expression level had a poor survival compared with the patients who had a lower level of the SNHG9 in the tumor tissues (p = 0.001)." (PMID 32294932, 2020). "In lung cancer, SNHG9 played a role in cisplatin resistance by promoting the CAPRIN1 gene, and the knockdown of SNHG9 decreased cell proliferation and invasion." (PMID 35887228, 2022). "Moreover, the knockdown of SNHG9 in lung cancer cells increased the percentage of cells in the G1/G0 phase by more than 10%, whereas it reduced the percentage of S phase at least 10%, as compared with cancer cells without knockdown of SNHG9 (all p < 0.05)." (PMID 32294932, 2020).
ovarian carcinoma (3 papers, 2021 to 2025). A malignant neoplasm originating from the surface ovarian epithelium. "SNHG9 suppresses the progression of ovarian cancer cells by regulating miR−214-5p/CRY2 axis, acting as a tumor suppressor gene." (PMID 41200835, 2025). "Three SNHGs, including SNHG2, SNHG9, and SNHG10, have been found to play a protective role in ovarian cancer." (PMID 41200835, 2025). "According to reported studies, in addition to SNHG2, SNHG5, SNHG9, and SNHG10, most SNHGs play a role as a proto-oncogene in the occurrence and progression of ovarian cancer via different pathways." (PMID 41200835, 2025).
liver cancer (2 papers, 2022 to 2026). An epithelial or non-epithelial malignant neoplasm that arises from the liver. "In vitro colony formation and tumor sphere formation assays showed that SNHG3, SNHG5, SNHG9, and DNACR enhance the stem‐like properties of liver cancer stem cells." (PMID 41474641, 2026). "Furthermore, in vivo experiments demonstrated that knocking down SNHG3, SNHG5, SNHG9, and DNACR inhibits the growth of liver cancer stem cells or reduces the expression of stem cell marker proteins in tumors." (PMID 41474641, 2026). "Moreover, decreasing SNHG9 reduced methylation of the GSTP1 gene and inhibited liver cancer cell proliferation, migration and invasion." (PMID 35887228, 2022).
Obesity (2 papers, 2023 to 2025). Accumulation of substantial excess body fat. "In addition, recent research has highlighted the critical role of the lncRNA-small nucleolar RNA host gene 9 (lncRNA-SNHG9) in the context of obesity-associated EVs." (PMID 39940780, 2025). "Forced expression of Snhg9 in the intestinal epithelium of conventional mice impaired lipid absorption, reduced body fat, and protected against diet-induced obesity." (PMID 37616368, 2023). "Furthermore, the research highlights a concerning trend: exosomes isolated from the plasma of individuals suffering from obesity display markedly lower levels of SNHG9." (PMID 39940780, 2025).
asthma (1 paper, 2024). "Overall, SNHG9, hsa-miR-615-3p and ACER3 might be viewed as effective therapeutic targets for asthma." (PMID 38297226, 2024). "However, the role of SNHG9 and hsa-miR-615-3p in asthma has not been reported in previous studies." (PMID 38297226, 2024). "In addition, SNHG9-hsa-miR-615-3p-ACER3 might be involved in asthma pathogenesis, and hsa-miR-212-5p and hsa-miR-5682 could be viewed as effective therapeutic targets for asthma." (PMID 38297226, 2024).
Cirrhosis (1 paper, 2022). A chronic disorder of the liver in which liver tissue becomes scarred and is partially replaced by regenerative nodules and fibrotic tissue resulting in loss of liver function. "In multivariate analysis, the presence of cirrhosis, advanced BCLC stages and elevated SNHG9 expression were selected as independent predictive factors of overall survival." (PMID 35887228, 2022).
endothelial dysfunction (1 paper, 2025). In vascular diseases, endothelial dysfunction is a systemic pathological state of the endothelium (the inner lining of blood vessels) and can be broadly defined as an imbalance between vasodilating and vasoconstricting substances produced by (or acting on) the endothelium. "Adipocyte-derived exosomal SNHG9 is down-regulated in obese individuals with endothelial dysfunction." (PMID 40941416, 2025). "SNHG9 can prevent endothelial dysfunction in obese patients by reducing inflammation and apoptosis." (PMID 40941416, 2025).
mesothelioma (1 paper, 2025). A usually malignant and aggressive neoplasm of the mesothelium which is often associated with exposure to asbestos. "Additionally, we identified other lncRNAs enriched in PM-EVs, such as SNHG9, SNHG11 and SNHG15, which have been previously associated with cancer development and were associated with mesothelioma patients’ survival in our analysis." (PMID 39920655, 2025).
myocardial infarction (1 paper, 2019). Gross necrosis of the myocardium, as a result of interruption of the blood supply to the area, as in coronary thrombosis. "By comparing the co-expression with ceRNA networks, five lncRNAs (SNHG9, LINC02202, UBAC2-AS1, PTCSC3 and myocardial infarction associated transcript (MIAT)) and 32 genes (such as PIK3R1, PTPRB) were found to be shared." (PMID 31534842, 2019).
osteoarthritis (1 paper, 2020). A noninflammatory degenerative joint disease occurring chiefly in older persons, characterized by degeneration of the articular cartilage, hypertrophy of bone at the margins and changes in the synovial membrane. "Our preliminary RNA-Seq data revealed altered expression of small nucleolar RNA host gene 9 (SNHG9) in osteoarthritis (OA) and its reverse correlation with miR-34a, which can regulate chondrocyte apoptosis in rat OA model." (PMID 32738890, 2020).
Papillary Thyroid Cancer (1 paper, 2021). "However, the function of SNHG9 in papillary thyroid cancer is still unknown." (PMID 34017682, 2021).
psoriasis (1 paper, 2023). An autoimmune condition characterized by red, well-delineated plaques with silvery scales that are usually on the extensor surfaces and scalp. "We found that in clinical skin samples, the expression levels of SNHG9, CALML3-AS1 in epidermal cell types were significantly higher in psoriasis than in the healthy group." (PMID 37822943, 2023). "To experimental validate the immunoregulatory potential of cell-type specific lncRNAs, we selected three lncRNAs (SNHG9, CALML3-AS1, and CARMN), and in silico examined their expression levels in different cell clusters under healthy and psoriasis conditions." (PMID 37822943, 2023).
cancer (13 papers, 2020 to 2025). A tumor composed of atypical neoplastic, often pleomorphic cells that invade other tissues. "It was recently discovered that small nucleolar RNA host gene 9 (SNHG9), a lncRNA widely implicated in cancer, binds to phosphatidic acid (PA) and LAST1 and induces liquid–liquid phase separation (LLPS)." (PMID 40863722, 2025). "SNHG9 knockdown inhibited DNA synthesis, cell cycle progression, and clonogenic ability, while upregulating cancer-related genes, suggesting its role in promoting PCa cell proliferation, migration, and invasion." (PMID 39530098, 2024). "SNHG9 (Small nucleolar RNA host gene 9) has been reported as a promising oncogenic lncRNA in various cancers." (PMID 35887228, 2022). "Although LncRNA SNHG9 is considered an oncogene in many cancers, the biological function and molecular mechanism of SNHG9 in HCC are still unclear." (PMID 33898523, 2021). "SNHG9 was highly expressed in ten (76.9%) of the 13 tested cancer cell lines compared with their normal counterpart." (PMID 32294932, 2020). "Knockdown of SNHG9 in cancer cells reduced the cell growth, proliferation, and invasion in vitro and tumorigenesis in vivo." (PMID 32294932, 2020). "In addition, the restriction of cancer cell growth and proliferation by the SNHG9 downregulation were accompanied by an accumulation of cells in the G1 phase and a decreased rate of S-phase." (PMID 32294932, 2020). "Small interfering RNAs specifically targeting SNHG9 (SNHG9-siRNA) were designed that could dramatically reduce SNHG9 expression level in the cancer cells with the treatment." (PMID 32294932, 2020). "Aphidicolin did not affect cell proliferation and migration states of the cancers treated with SNHG9 knockdown, suggesting that the phenotype was independent of cell proliferation and migration." (PMID 32294932, 2020).